APOE (apolipoprotein E)
Diseases named in the same sentence as APOE in open-access papers (continued):
Sharing a sentence is not in itself a finding about the gene and the disease.
atherosclerosis (continued). "Our group previously reported that the subcutaneous infusion of human native glucagon-like peptide-1 (GLP-1) suppressed the development of atherosclerotic lesions in apolipoprotein E-null (Apoe−/−) mice, a representative animal model of atherosclerosis." (PMID 23967137, 2013). "To study the interplay between angiotensin II and ROS during the development of atherosclerosis, we applied hypercholesterolemic ApoE−/− mice, which are prone to atherosclerosis and reproduce many features of atherosclerosis in patients." (PMID 23801967, 2013). "Genetic deficit or pharmacological blockade of angiotensin receptor 1 (AT1R) attenuates atherosclerosis and improves endothelial function in experimentally induced diabetes in ApoE−/− mice via peroxisome proli-ferator-activated receptor γ (PPARγ) pathway." (PMID 23547749, 2013). "In animals with diet-induced atherosclerosis, ApoE/nNOS knockout mice had more severe atherosclerosis than those with ApoE knockout alone." (PMID 24082858, 2013). "Research on anti-MCP-1 gene therapy has successfully gained the attenuation of atherosclerosis in ApoE-deficient mice, suggesting MCP-1 as a potential therapeutic target in atherosclerosis." (PMID 24129228, 2013). "The current study demonstrates that a 9-cis-β-Carotene-rich diet provided as Dunaliella powder lowers plasma cholesterol levels and inhibits atherosclerosis progression in high-fat diet fed apoE−/− mice." (PMID 24175283, 2013). "As the role of FGF in atherosclerosis is much less documented than its role in restenosis, we checked the presence of FGF and its receptors in atherosclerotic lesions of apoE-deficient mice and found high expression of FGFR1 and the FGFR ligands FGF1 and FGF2." (PMID 24224032, 2013). "Exposure of apoE−/− male mice, in utero or neonatally, to this dose significantly increased atherosclerosis in adulthood relative to controls to a similar extent for both exposure regimens." (PMID 23825571, 2013). "Regulatory T-cell response to Apolipoprotein B100–derived peptides was shown to reduce the development and progression of atherosclerosis in ApoE−/− Mice." (PMID 23505495, 2013). "A number of laboratories have applied metabolomics to understand the progression of atherosclerosis in the apolipoprotein E (ApoE)*3Leiden mouse or the atherogenic ApoE gene knock-out (ApoE-/-) mouse model." (PMID 24252331, 2013). "A pronounced Ly6G+ cell intraplaque recruitment was also observed during early stages of atherosclerosis in TMPro/Pro:ApoE−/− mice." (PMID 23409043, 2013). "We have previously shown that 20 weeks of diabetes significantly enhances pro-inflammatory and pro-atherogenic mediators as well as atherosclerosis and diabetic kidney disease in ApoE/GPx1 dKO mice." (PMID 23874911, 2013). "Other subsets of CD4+ Treg cells, such as T-helper cell type 3 (Th3) and type 1 Treg (Tr1) cells, were also shown to attenuate atherosclerosis in apolipoprotein E-knockout mice." (PMID 24385687, 2013). "Additional effects on atherosclerosis were found in a model of LDL receptor knockout mice, as well as in APOE knockout model, where DPP4i was associated with less atherosclerosis." (PMID 23537430, 2013). "Recently, safrole-2′,3′-oxide (main component of sassafras oil in nutmeg) which is found in cola beverages, has been reported to aggravate atherosclerosis in ApoE−/− mice." (PMID 23547749, 2013). "Chai and colleagues generated mice overexpressing human HAS2 under the control of the αSMA promoter, and crossed these mice with apoE–/– mice, and showed that overproduction of HA in the aorta of apoE–/– mice accelerated the development of atherosclerosis." (PMID 23484050, 2013). "ApoE−/− mice have decreased serum apolipoprotein E and exhibit lipid abnormalities and atherosclerosis even on a low-cholesterol diet." (PMID 23799016, 2013).
atherosclerosis (continued). "In order to study the impact of this drug on murine lupus disease including premature atherosclerosis development, we treated gld.apoE−/− mice, a model of SLE and accelerated atherosclerosis, with MMF." (PMID 23577189, 2013). "To investigate the effect of celastrol on development of atherosclerosis in vivo, we chose the apoE−/− mouse." (PMID 23799016, 2013). "The observations made in this study support that apoE, having a central role as an anti-inflammatory molecule, constitutes a potential therapeutic target in atherosclerosis and other inflammatory-related diseases." (PMID 24244577, 2013). "Shah and Chyu found that D-4F reduced vein graft atherosclerosis in apoE null mice fed a western diet." (PMID 23781332, 2013). "Conversely, endothelial specific Arg-II transgenic mice on ApoE−/− background show accelerated atherosclerosis." (PMID 23781221, 2013). "The ApoE−/− mouse, a recognized atherosclerosis animal model, can spontaneously develop atherosclerosis with features similar to those observed in human hyperlipoproteinemia." (PMID 23941539, 2013). "In conclusion, our study suggests that a HFD induces the development of atherosclerosis in the ApoE knockout mouse aortic vessel wall, especially in the intima area, through the IKKε-mediated NF-κB pathway." (PMID 23741427, 2013). "The specific interaction of apoE4 with estrogen, even though their vasculature is less affected than that of apoE ko mice (hypercholesterolemia and accelerated atherosclerosis), results in a deleterious effect in the form of a loss of synapses." (PMID 26316992, 2013). "Although high-fat diet fed ApoE-/- mice are regularly used in preclinical atherosclerosis studies, the cholesterol levels obtained are extremely high." (PMID 24324556, 2013). "Contrary to the pro-inflammatory cytokines, which play a pivotal role in inducing and maintaining inflammation, macrophage-produced apoE has been shown to play an equally important but protective role in atherosclerosis." (PMID 24244577, 2013). "The development and severity of atherosclerosis in these mice is increased further when they are fed a high fat diet, making the high fat diet-fed ApoE KO mouse a useful model to study advanced atherosclerotic plaque development." (PMID 24205352, 2013). "The effect of SSR128129E was therefore assessed in a mouse model of vein graft arteriosclerosis as well as the apoE-KO model of atherosclerosis." (PMID 24224032, 2013). "We observed that sildenafil treatment, in addition to amelioration of endothelial function in hypercholesterolemic apoE−/− mice, is capable of reducing atherosclerosis in the aorta of treated animals by approximately 40%." (PMID 23289368, 2013). "While apoE is believed to play an important protective role in atherosclerosis, the reverse is true for T cells." (PMID 24244577, 2013). "The potential role of PTX3 in atherosclerosis was recently addressed in PTX3/apolipoprotein E (ApoE) double knockout mice." (PMID 23690668, 2013). "Our results have shown that the modified Eb analogue, ME, attenuates oxidative stress, atherosclerosis and the hallmarks of diabetic nephropathy in the diabetic ApoE/GPx1 dKO mouse." (PMID 23874911, 2013). "On the other hand, elevated plasma ApoE levels reduced hyperlipidemia and atherosclerosis such as in the transgenic mouse models with macrophage-specific ApoE expression." (PMID 23451244, 2013). "Conversely, transplantation of BM from wild type mice into lethally irradiated SR-BI/apoE dKO mice rescues their survival and reduces aortic and CA atherosclerosis." (PMID 23967310, 2013). "It would be significant to understand the effects of apolipoprotein E (apoE), which plays an important role in lipoprotein metabolism and atherosclerosis." (PMID 23656756, 2013). "Site specific effects on atherosclerosis have been described previously in ApoE-/- mice in response to various compounds or genetic modifications." (PMID 24324556, 2013).
atherosclerosis (continued). "Several recent reports have revealed that dipeptidyl peptidase (DPP)-4 inhibitors have suppressive effects on atherosclerosis in apolipoprotein E-null (Apoe−/−) mice." (PMID 23967137, 2013). "Previous work also showed that decorin overexpression reduced atherosclerosis development in ApoE KO mice, supporting a protective role for decorin in vascular diseases." (PMID 24205352, 2013). "The severely compromised vasculature in apoE ko mice (severe atherosclerosis, impaired vascular endothelium-dependent relaxation, and aortic stiffening) results in a compensatory effect by increased neurogenesis." (PMID 26316992, 2013). "We also report that macrophage-derived apoE–dependent atherosclerosis suppression is proportional to the extent of plasma cholesterol lowering." (PMID 22606237, 2012). "Macrophage-derived 12/15-LO plays an essential role in the development of atherosclerosis in the apoE-/- model." (PMID 22973824, 2012). "We determined the effects of fructose feeding on the development of atherosclerosis in arteries from ApoE-KO mice." (PMID 22474431, 2012). "In accordance with our previous reports, the development of atherosclerosis is potently ameliorated in an environment where atherogenic B2 cells but not atheroprotective B1a cells are reduced, as occurs in BAFF-R-deficient ApoE−/− mice." (PMID 22238605, 2012). "In 2011, our group reported that GLP-1 and glucose-dependent insulinotropic polypeptide (GIP), two native incretins, elicited anti-atherogenic effects in apolipoprotein-E-null (Apoe−/−) mice, an animal model of atherosclerosis." (PMID 22536426, 2012). "Detailed analysis of FDG-6-P accumulation was performed in the carotid arteries of Western diet fed ApoE KO mice where atherosclerosis was accelerated by ligation of the left common carotid artery." (PMID 23209718, 2012). "Macrophage-derived apoE raises plasma apoE levels in response to diet-induced hyperlipidemia and by such reduces atherosclerosis proportionally to the extent to which it lowers plasma cholesterol levels." (PMID 22606237, 2012). "As expected, atherosclerosis is increased in IL-10−/− mice and IL-10−/−/ApoE−/− double knock-out mice." (PMID 22844641, 2012). "We generated BAFF-R−/− ApoE−/− (BaffR.ApoE DKO) mice by crossing C57Bl/6 BAFF-R−/− mice with atherosclerosis-prone C57Bl/6 ApoE−/− (ApoE KO) mice." (PMID 22238605, 2012). "The treatment of ApoE knockout mice with recombinant IL-12 aggravated atherosclerosis progression, and higher plasma IL-12 levels were also confirmed as a biomarker in CAD patients." (PMID 23285065, 2012). "The most clearly observable phenotype of ApoE-gene-knockout mice is the spontaneous development of atherosclerotic lesions which highly resemble human atherosclerosis combined with the spontaneous development of arterial vascular remodeling." (PMID 22811752, 2012). "We have demonstrated that FDG-6-P accumulation was significantly increased in aortas of Western diet-fed ApoE KO mice (a model of spontaneous atherosclerosis) as well as in ligated carotid arteries of ApoE KO mice (a model of accelerated atherosclerosis)." (PMID 23209718, 2012). "Among the animal models of heart failure, the major limitation of the apoE-/- mouse is the infrequency of coronary plaques and thrombosis, two common complications of human atherosclerosis, as recently reviewed." (PMID 22330242, 2012).
atherosclerosis (continued). "Liver-directed ApoE gene transfer to these mice retarded progression of atherosclerosis by 38% during the 70-day study period, with a progressive decline in ApoE levels and no evoked humoral immune response." (PMID 22482072, 2012). "Other studies that used ex vivo autoradiography or scintillation counting demonstrated, however, increase in FDG uptake in aortas of ApoE-KO mice with atherosclerosis." (PMID 23209718, 2012). "The effects of eNOS deletion on total vascular NO and superoxide productions in atherosclerotic apoE−/− mice were studied with an aim to determine which of these two radicals largely determine the key events in atherosclerosis." (PMID 22291917, 2012). "We also demonstrate that in our model, macrophage-derived apoE decreases atherosclerosis but only to the extent to which it lowers plasma cholesterol levels." (PMID 22606237, 2012). "Overexpression of MGP in the apoE−/− mouse model of atherosclerosis reduced both intimal and medial calcification of atherosclerotic plaques whereas gene deletion of MGP in apoE−/− mice accelerated intimal calcification of plaques." (PMID 22952653, 2012). "Passive administration of recombinant human antibodies against aldehyde-modified apolipoprotein B-100 peptide sequences was observed to inhibit atherosclerosis in ApoE−/− mice." (PMID 22957222, 2012). "We show that lack of endogenous NO production by eNOS accelerates L/E-interactions in apoE atherosclerosis." (PMID 22291917, 2012). "In apoE-/- mice, positive remodeling has been reported in aortas at both early and late stages of atherosclerosis." (PMID 22330242, 2012). "Using P. gingivalis strains that have been previously evaluated in the ApoE null atherosclerosis model, we assessed the ability of W83, A7436, 381, and 33277 to adhere, invade, and persist in human coronary artery endothelial (HCAE) cells." (PMID 23300720, 2012). "This study examined the contribution of macrophage-derived apoE expression levels on the modulation of diet-induced hypercholesterolemia and atherosclerosis." (PMID 22606237, 2012). "In ApoE−/− mice, the number of Th17 cells tended to increase as a function of time, tightly paralleling continuing development of atherosclerosis." (PMID 22577258, 2012). "ApoE-/- mouse is a well-established animal model for studying atherosclerosis, but, the pathogenesis in these mice is strikingly different from that of human atherosclerosis." (PMID 22762542, 2012). "In support of this possibility, Ahr null mice exhibit decreased atherosclerosis in the ApoE null background." (PMID 22833723, 2012). "In order to achieve these aims, we generated ApoE/GPx1 double KO (dKO) mice and rendered them diabetic using STZ, which proved to be a robust model for diabetes-associated atherosclerosis and nephropathy." (PMID 22013533, 2012). "The apolipoprotein E (APOE) mouse model is also routinely utilized to study the events that are responsible for atherosclerosis pathogenesis." (PMID 23087690, 2012). "As we observed a large increase in adventitial immune cell accumulation in aged ApoE−/− mice, the possibility that immune senescence contributes to atherosclerosis deserves attention." (PMID 22783198, 2012). "We recently reported that glucose-dependent insulinotropic polypeptide (GIP) prevents the development of atherosclerosis in apolipoprotein E-null (Apoe−/−) mice." (PMID 22536426, 2012). "Two decades ago, the first gene-targeted murine model of atherosclerosis was created by the inactivation of the apolipoprotein E (apoE) gene by homologous recombination." (PMID 22330242, 2012). "In our study, we have investigated for the first time the role of Arg‐II in atherosclerosis with a genetic approach, by generating ApoE−/−Arg‐II−/− double‐knockout mice." (PMID 23130157, 2012).
atherosclerosis (continued). "As stated in the introduction, the ApoE−/− mouse on a Western diet is a well-characterized model of atherosclerosis with high blood levels of cholesterol, HDL and LDL contributing to the formation of plaques in peripheral blood vessels (data not shown)." (PMID 22709928, 2012). "We evaluated the sensitivity and specificity of IntegriSense in the detection of atherosclerotic lesions in the apoE−/− mice model of atherosclerosis and compared it to the cathepsin-activatable agents." (PMID 23119157, 2012). "We have demonstrated that 18F-FDG can be used to follow the progression of atherosclerosis in apoE−/− mice." (PMID 23226424, 2012). "In line with this, ApoE/IL-1R double knockout mice are protected from atherosclerosis, compared to ApoE−/− controls." (PMID 24832046, 2012). "SR-BI protects against early-onset atherosclerosis using SR-BI/apolipoprotein E double homozygous knockout mice." (PMID 23133640, 2012). "Pathophysiologically, the Th17/IL-17+ cells directly support the development of atherosclerosis in ApoE−/− mice." (PMID 22577258, 2012). "In this study, we have demonstrated that 18F-FDG can be used to follow the progression of atherosclerosis in apoE−/− mice." (PMID 23226424, 2012). "During the course of aging, PTX3−/− apoE−/− mice develop, in line with expectations, increasing atherosclerosis as a function of time." (PMID 22577258, 2012). "Ablation of endothelial caveolin-1 protects ApoE−/− mice (a mouse model of atherosclerosis), from developing atherosclerosis." (PMID 22479476, 2012). "ApoE−/− mice are created by targeted gene inactivation, and are considered to be a relevant model for atherosclerosis because they are hypercholesterolemic and develop spontaneous arterial lesions." (PMID 22536886, 2012). "In order to reveal impact of VKA treatment on plaque stability we studied effects of warfarin on plaque calcification and phenotype in the apoE−/− mouse model of atherosclerosis." (PMID 22952653, 2012). "Using these agents, fluorescence molecular tomography (FMT) and computed tomography (CT) have been applied to quantitatively evaluate the levels of inflammation in the mouse apoE−/− models of atherosclerosis." (PMID 23119157, 2012). "This study examined the contribution of macrophage-derived apoE expression levels in diet-induced hyperlipidemia and atherosclerosis." (PMID 22606237, 2012). "Compared with control ApoE−/− mice, however, transgenic mice developed significantly less atherosclerosis after 24 weeks on the WTD, as indicated by plaque area en face of the aorta from below the arch down to the iliac bifurcation." (PMID 22829904, 2012). "We found that a similar ∼50% reduction in atherosclerosis as assessed by CD68-stained macrophage accumulation in BaffR.ApoE DKO mice (p<0.05)." (PMID 22238605, 2012). "The present study aims to exploit bioinformatic tools in order to analyze microarray data of atherosclerotic aortic lesions of ApoE knockout mice, a model widely used in atherosclerosis research." (PMID 23193398, 2012). "Another study has shown that apoptosis, oxidative stress and progression of atherosclerosis in apoE−/− mice can be positively influenced by treatment with humanin." (PMID 22382745, 2012). "A major finding of this study is that macrophages can respond to diet-induced hypercholesterolemia by raising plasma apoE levels and thereby reduce plasma cholesterol levels and atherosclerosis." (PMID 22606237, 2012).